FERMT3 (FERM domain containing kindlin 3)
Description:
Plays a central role in cell adhesion in hematopoietic cells. Acts by activating the integrin beta-1-3 (ITGB1, ITGB2 and ITGB3) (By similarity). Required for integrin-mediated platelet adhesion and leukocyte adhesion to endothelial cells. Required for activation of integrin beta-2 (ITGB2) in polymorphonuclear granulocytes (PMNs) (By similarity). Isoform 2 may act as a repressor of NF-kappa-B and apoptosis.
Synonyms: KIND3; MIG2B; URP2; MGC10966; UNC112C; MIG-2; URP2SF
Tractability: Antibody: its Gene Ontology location is reachable by antibodies, with high confidence. PROTAC: ubiquitination databases record sites on it; its protein half-life has been measured.
Gene: Protein-coding gene on chromosome 11 (64,205,926 to 64,223,896, forward strand). Ensembl gene ENSG00000149781.
Subcellular location: Cell projection, podosome
Subcellular location (Human Protein Atlas): Vesicles
Pathways (Reactome):
Hemostasis: Platelet degranulation
Gene Ontology:
Molecular function: lipid binding; integrin binding
Biological process: integrin activation; integrin-mediated signaling pathway; leukocyte cell-cell adhesion; platelet aggregation; positive regulation of cell migration; regulation of cell-cell adhesion mediated by integrin; substrate adhesion-dependent cell spreading; cell-matrix adhesion
Cellular component: extracellular exosome; membrane; cell-substrate junction; extracellular region; platelet alpha granule lumen; podosome
Genetic constraint (gnomAD): Loss-of-function variants: 33 observed, 79.35 expected, observed/expected ratio (o/e) 0.42, 90% interval 0.31 to 0.56. The upper end of that interval is the gene's LOEUF score, 0.56, which puts it in group 2 of 6, group 1 being the genes least tolerant of losing a copy. Missense variants: 754 observed, 914.61 expected, observed/expected ratio (o/e) 0.82, 90% interval 0.78 to 0.88. Synonymous variants: 375 observed, 375.04 expected, observed/expected ratio (o/e) 1, 90% interval 0.92 to 1.09.
Gene-disease validity (ClinGen):
ClinGen rates the evidence that FERMT3 causes each of these diseases.
leukocyte adhesion deficiency 3 (autosomal recessive): Definitive.
Homologues: Orthologues: macaque FERMT3 (99% identical), dog FERMT3 (97% identical), chimpanzee FERMT3 (96% identical), pig FERMT3 (95% identical), mouse Fermt3 (94% identical), rat Fermt3 (94% identical), guinea pig FERMT3 (93% identical), zebrafish fermt3b (62% identical), tropical clawed frog fermt3 (62% identical), zebrafish fermt3a (59% identical), Drosophila melanogaster Fit1 (42% identical), Drosophila melanogaster Fit2 (42% identical), and 1 more. Paralogues in human: FERMT1 (56% identical), FERMT2 (54% identical).
Diseases named in the same sentence as FERMT3 in open-access papers:
FERMT3 is named in the same sentence as 66 diseases in open-access papers, as found by Europe PMC text mining. Sharing a sentence is not in itself a finding about the gene and the disease. The quoted sentences say what the papers report.
Leukocyte adhesion deficiency type III (11 papers, 2014 to 2026). Leukocyte adhesion deficiency type III (LAD-III) is a form of LAD (see this term) characterized by both severe bacterial infections and a severe bleeding disorder. "Pathogenic variants in FERMT3 that alter expression or function of Kindlin-3, cause a severe autosomal recessive disease known as leukocyte adhesion deficiency type III (LADIII) (OMIM 612840)." (PMID 41301446, 2025). "Kindlin-3 (also known as FERMT3) is generally expressed in the notochord, central nervous system, cement gland, and etc., mutations in which can contribute to leukocyte adhesion deficiency type III." (PMID 30386175, 2018). "Ncf2 is a causal gene for chronic granulomatous disease, while mutations in Fermt3 lead to leukocyte adhesion deficiency, type 3." (PMID 25115202, 2014). "FERMT3 deficiency results in leukocyte adhesion deficiency type III (LAD-III) that is the pathology characterized by severe platelet dysfunction and Glanzmann-thrombasthenia-like bleedings associated to hyperleukocytosis and immune deficiency and, inconstantly, osteopetrosis." (PMID 32041177, 2020). "Likewise, leukocyte adhesion deficiency, type III patients, who have loss-of-function mutations in FERMT3 (the gene encoding for kindlin-3) do not suffer from thrombocytopenia." (PMID 28743899, 2017).
osteopetrosis (8 papers, 2014 to 2024). Osteopetrosis, also known as marble bone disease, is a descriptive term that refers to a group of rare, heritable disorders of the skeleton characterized by increased bone density on radiographs. "Mutations in FERMT3 (fermitin family member 3) gene have been reported to cause osteopetrosis in association with leukocyte adhesion deficiency type III (LAD III)." (PMID 30837952, 2019). "Mutations in the FERMT3 and CALDAGGEF1 genescause osteopetrosis combined with leukocyte adhesion deficiencytype III (LAD III)." (PMID 37465191, 2023).
breast cancer (7 papers, 2014 to 2021). A primary or metastatic malignant neoplasm involving the breast. "Previous research showed that FERMT3 was overexpressed in breast cancer and enhances cancer invasion and metastasis." (PMID 33934696, 2021). "It was reported that FERMT3 was down-regulated and plays a tumor suppressor in many solid tumors including breast cancer, melanoma, as well as lung cancer." (PMID 33934696, 2021). "It has been reported that reduced expression of FERMT3 in breast cancer promotes metastasis formation by mediating β3-integrin activation." (PMID 34604090, 2021). "With regard to FERMT3 (also known as Kindlin-3), whether this gene plays a suppressing or promoting role in breast cancer progression is still controversial." (PMID 34604090, 2021). "Moreover, FERMT3 expressed in the TME is correlated with a poor prognosis of breast cancer patients, which is inconsistent with our finding that FERMT3 could serve as a protective prognostic factor in TNBC." (PMID 34604090, 2021). "As for the three protective genes, the prognostic value of FERMT3 and RASSF2 has been noted in breast cancer, while that of RASSF5 has not." (PMID 34604090, 2021).
melanoma (7 papers, 2014 to 2026). A malignant, usually aggressive tumor composed of atypical, neoplastic melanocytes. "Studies have shown that loss of Kindlin-3 increased mesenchymal stem cell proliferation and FERMT3 was downregulated in several tumor types namely melanoma, breast, and lung cancers, and plays a tumor suppressor role in solid cancer by regulating cell adhesion, migration and invasion." (PMID 34742298, 2021). "We excluded the following genes that were methylated and deleted in melanoma: PTEN, BRIMS1, FERMT3 (KIND3), AKAP12 (SSeCKS), CDKN2A, APAF-1, MTAP and MEN1." (PMID 34639015, 2021).
Immunodeficiency (6 papers, 2018 to 2025). Failure of the immune system to protect the body adequately from infection, due to the absence or insufficiency of some component process or substance. "LAD type 2 (LAD2) is caused by mutations in the SLC35C1 gene leading to a generalized loss of expression of fucosylated glycans on the cell surface and LAD type 3 (LAD3) is caused by mutations in the FERMT3 gene resulting in platelet function defects along with immunodeficiency." (PMID 33391282, 2020). "In this case study, we described a novel homozygous mutation in the FERMT3 gene (c.1683-22_1683-19del) in a family with LAD-III, an autosomal recessive disorder with immune dysfunction and bleeding tendencies." (PMID 40078257, 2025). "Several studies have demonstrated that mutations in FERMT3 can lead to leukocyte adhesion deficiency syndrome type 3 (LAD3), resulting in defective platelet function and immunodeficiency." (PMID 38255822, 2024).
bleeding disorders (4 papers, 2009 to 2026). "For example, both agonists studied induced significant changes in phosphorylation sites of SEPT5 and FERMT3, and deficiency of these proteins causes bleeding disorders associated with platelet defects." (PMID 24400094, 2014).
lung carcinoma (4 papers, 2014 to 2024). "It was found that FERMT3 expression was down-regulated in lung cancer, and depletion of FERMT3 enhances cell proliferation, migration, and invasion in lung cancer cells." (PMID 34742298, 2021). "Previous studies have indicated FERMT3 is downregulated and plays a tumor-suppressive role in lung cancer." (PMID 34742298, 2021). "Our study provides a new perspective for understanding EMT and suggests that FERMT3 is a potential target for further understanding of the mechanisms of COPD and lung cancer." (PMID 34742298, 2021).
glioma (3 papers, 2021 to 2024). A benign or malignant brain and spinal cord tumor that arises from glial cells (astrocytes, oligodendrocytes, ependymal cells). "The findings of several recent studies have indicated that OLFML3, EVA1B, and FERMT3 are potential prognostic markers for glioma, which are significantly associated with poor prognosis and tumor immune microenvironment." (PMID 38686055, 2024).
leukocyte adhesion deficiency (3 papers, 2013 to 2022). Leukocyte adhesion deficiency (LAD) is a primary immunodeficiency characterized by defects in the leukocyte adhesion process, marked leukocytosis and recurrent infections. "There is evidence showing that the genetic mutations in Fermt3 lead to changes in integrin activation that can further cause leukocyte adhesion deficiency." (PMID 34679887, 2021).
anemia (2 papers, 2016 to 2018). A reduction in the number of red blood cells, the amount of hemoglobin, and/or the volume of packed red blood cells. "To test whether kindlin-3 expression is required for thymopoiesis, we investigated thymus morphology and size in kindlin-3-deficient (Fermt3-/-) mice, which die of severe bleedings and anemia within the first week after birth." (PMID 30187863, 2018).
COVID-19 (2 papers, 2021 to 2025). A disease caused by infection with severe acute respiratory syndrome coronavirus 2. "GNB1 showed the largest increase in the plasma of PLWH with COVID-19, followed by PTPN6, FERMT3, and PSTPIP2." (PMID 40568587, 2025).
glioblastoma (2 papers, 2019 to 2021). The most malignant astrocytic tumor (WHO grade IV). "A previous study reported that FERMT3 contributed to the occurrence of glioblastoma through activation of the Wnt pathway." (PMID 34742298, 2021).
Stroke (2 papers, 2019 to 2023). Sudden impairment of blood flow to a part of the brain due to occlusion or rupture of an artery to the brain. "In the current study, LASSO regression analysis and random forest algorithms found two signature genes, then three validation datasets, including GSE140275, GSE122709, and GSE180470, confirmed that SDHD and FERMT3 were highly expressed in the stroke group." (PMID 36968495, 2023). "In conclusion, we identified two signature genes (SDHD and FERMT3) in peripheral blood of stroke patients by machine learning." (PMID 36968495, 2023). "The results showed that SDHD was substantially upregulated in the stroke group, while the same trend was seen in expression of FERMT3." (PMID 36968495, 2023). "SDHD and FERMT3 were highly expressed in the stroke group, suggesting that these genes may play a significant role in stroke." (PMID 36968495, 2023). "SDHD and FERMT3 were found to be significantly associated with depression, and were identified as diagnostic and therapeutic signatures by our stroke cohorts with and without PSD, which could be a valuable reference for future clinical practice." (PMID 36968495, 2023). "SDHD and FERMT3 presented higher expression in the PSD group than the non-PSD group, indicating their potential roles in diagnosis of depression in stroke patients." (PMID 36968495, 2023).
adenoma (1 paper, 2025). A neoplasm arising from the epithelium. "Among these, APOA4, FERMT3, and FLNA exhibited consistent expression changes in the adenoma groups of both cohorts." (PMID 41367384, 2025). "Based on the consistency of their expression changes in the adenoma groups across both cohorts and their differential expression between inflammatory polyps and adenomas, we selected APOA4 and FLNA for further investigation, while excluding FERMT3 and THBS1." (PMID 41367384, 2025).
aneurysm (1 paper, 2022). Bulging or ballooning in an area of an artery secondary to arterial wall weakening. "PCOLCE, CORO1A, and FERMT3/KINDLIN3 in the combined networks suggest a role for collagen turnover and angiogenesis, platelet function, and integrin biology pathways also identified in the murine aneurysm proteomes." (PMID 35990960, 2022).
autism (1 paper, 2023). Persistent deficits in social interaction and communication and interaction as well as a markedly restricted repertoire of activity and interest as well as repetitive patterns of behavior. "More notably, LAMP1 also interact with ITGAL, FYN and FERMT3 which were dysregulated in our blood biomarker screening results, suggesting that these proteins involved in focal adhesion and immune regulation may play a vital role in autism." (PMID 37640746, 2023).
depression (1 paper, 2023). "Based on GSEA analysis of two signature genes (SDHD and FERMT3), we found that they have a significant correlation with depression." (PMID 36968495, 2023).
gouty arthritis (1 paper, 2025). "Additionally, the co-regulatory ceRNA network mediated by circRNA and lncRNA, which upregulates miR550a-5p and miR550a-3-5p, thereby downregulating the expression of PSME1, FERMT3, GRK2, and OS9, can exacerbate gouty arthritis in vitro." (PMID 41311848, 2025).
osteosarcoma (1 paper, 2022). A usually aggressive malignant bone-forming mesenchymal neoplasm, predominantly affecting adolescents and young adults. "Through the comprehensive integration of GO, KEGG pathway analysis, and Cytoscape software analysis results, four osteosarcoma key genes, MMP9, FERMT3, CSF1R, and VWF, were finally identified." (PMID 35814015, 2022). "In the study, by the method of bioinformatics analysis, the possible key genes of osteosarcoma including MMP9, FERMT3, CSF1R, and VWF were screened from two microarray datasets, GSE12865 and GSE36001." (PMID 35814015, 2022).
renal carcinoma (1 paper, 2024). A carcinoma arising from the epithelium of the renal parenchyma or the renal pelvis. "An increase in FERMT3 mRNA expression was associated with a significant stage-specific increase only in renal cancer and uveal melanoma." (PMID 38548811, 2024).
Sepsis (1 paper, 2024). Sepsis is defined as life-threatening organ dysfunction caused by a dysregulated host response to infection. "The results indicated that both CD3G and FERMT3 play crucial roles in the immune system during sepsis." (PMID 38255822, 2024). "In our study, bioinformatics analysis revealed a positive correlation between FERMT3 and the SOFA score, and further confirmation showed a significant increase in FERMT3 expression in CLP sepsis mice." (PMID 38255822, 2024). "Furthermore, the correlation between these hub genes and downstream cytokines in sepsis mice was substantiated, suggesting that FERMT3 and CD3G, as upstream molecules, may possess more stable characteristics for diagnosis compared with downstream cytokines." (PMID 38255822, 2024). "To further validate the accuracy and potential of the hub genes FERMT3 and CD3G in sepsis diagnosis, we conducted correlation analysis between the expression of these genes in sepsis mice and the levels of typical inflammatory cytokine in vivo." (PMID 38255822, 2024).
spondyloarthritis (1 paper, 2025). "Out of the eight co-expressed highly expressed proteins, S100A8, S100A9, SERPING1, CECR1, and FERMT3 are all associated with inflammation, with S100A8 and S100A9 being clinically confirmed to be closely related to spondyloarthritis." (PMID 39877611, 2025). "It is evident that the high expression of S100A8, S100A9, SERPING1, ZYZ, VCL, and FERMT3 is positively correlated with spondyloarthritis." (PMID 39877611, 2025).
thyroid cancer (1 paper, 2024). "Downregulation of FERMT3 is seen lung, pancreatic, and thyroid cancers." (PMID 38548811, 2024).
tumor (17 papers, 2010 to 2024). "Data from single-cell RNA-sequencing revealed that FERMT3 was largely expressed in microglial cells and tissue-resident macrophages within the glioblastoma tumours." (PMID 39641590, 2024). "The complex that consists of integrin subunit α6 (ITGA6) and subunit β4 (ITGB4) and sequentially interacts with laminin and kindlin-3 (FERMT3) is involved in tumorigenesis by modulating tumor cell–ECM interaction." (PMID 32326232, 2020). "Fermitin family member 3 (FERMT3) promoted the blockage of PD-L1 by FERMT3-mediated Wnt/β-catenin signalling to suppress CRC cell invasion, 5-FU resistance and NK cells-mediated tumour killing." (PMID 36766788, 2023). "The expression levels of FERMT1 and FERMT2 were remarkably distinct in different tumor stages of LUAD and LUSC, while there was no significance between FERMT3 and different tumor stages." (PMID 33934696, 2021).
FERMT3 also shares sentences with these, for which no sentence is quoted: cancer (11 papers); chronic myeloid leukemia (3); infection (3); Venous thrombosis (3); breast tumor (2); myocardial infarction (2); acute myeloid leukemia (1); acute myocardial infarction (1); atherosclerosis (1); Atrophy (1); bacterial infections (1); bladder cancers (1); Bradycardia (1); cardiovascular diseases (1); Chediak-Higashi syndrome (1); chronic granulomatous disease (1); cognitive decline (1); colon cancers (1); colorectal cancer (1); deep vein thrombosis (1); Glanzmann thrombasthenia (1); hemangioma (1); hepatocellular carcinoma (1); Insulin resistance (1); iron deficiency (1); kidney cancer (1); Leukocyte-Adhesion Deficiency Syndrome (1); osteosclerosis (1); ovarian carcinoma (1); parasitic infectious disease (1).
A further 12 diseases each share a sentence with FERMT3 in 1 paper.